ENSG00000274086
Gene: Miscellaneous RNA gene on chromosome X (147,911,822 to 147,911,948, forward strand). Ensembl gene ENSG00000274086.
Gene Ontology:
Biological process: negative regulation of apoptotic process